CCDC25 (coiled-coil domain containing 25)
Diseases named in the same sentence as CCDC25 in open-access papers (continued):
Sharing a sentence is not in itself a finding about the gene and the disease.
cancer (56 papers, 2020 to 2026). A tumor composed of atypical neoplastic, often pleomorphic cells that invade other tissues. "One such protein, CCDC25, has been identified to be associated with neutrophil extracellular trap binding, emerges as a novel candidate in cancer research, yet its oncogenic role in ccRCC remains underexplored." (PMID 38570766, 2024). "This cellular motility was mediated by the cancer cell-resident transmembrane NET-DNA receptor coiled-coil domain containing 25 (CCDC25) which activates the integrin-linked kinase (ILK)-β-parvin pathway and thus senses extracellular DNA release." (PMID 35574410, 2022). "In addition, CCDC25 is a target molecule for the neutrophil extracellular traps (NETs) associated with cancer metastasis." (PMID 36211267, 2022). "CCDC25 expression by primary cancer cells has been associated with poor clinical outcomes." (PMID 35159247, 2022). "We recently identified CCDC25 as a NET-DNA sensor that is overexpressed on the cancer cell membrane and promotes cancer metastasis." (PMID 41480760, 2026). "They identified CCDC25 (Coiled-coil domain containing 25) on cancer cell membranes as binding to NET DNA, triggering a signaling cascade that promotes metastatic growth." (PMID 40599866, 2025). "On the tumour side, receptors, such as toll-like receptors and CCDC25, are instrumental in mediating cancer cell responses to NETs, including enhanced migration and survival." (PMID 40993312, 2025). "NET-DNA, via its transmembrane receptor CCDC25, can act as a chemotactic agent for cancer cells, promoting the mobility of tumor cells by triggering the ILK-β-parvin signaling cascade." (PMID 39687628, 2024). "This study explored a new anti-NETs strategy, and the first proposed anti-CCDC25 therapy showed promise for inhibiting cancer metastasis." (PMID 38369519, 2024). "In humans, CCDC25 is a transmembrane protein that acts as a receptor for NET-DNA on the cell membrane of cancer cells and can sense extracellular DNA." (PMID 39226151, 2024). "The transmembrane protein CCDC25 functions as a receptor for NETs-DNA on the surface of cancer cells, activating the ILK/β-parvin/RAC1 pathway and enhancing cancer cell motility by sensing extracellular NETs-DNA." (PMID 38664728, 2024). "We first analyzed the expression of CCDC25 across a spectrum of cancers, observing that CCDC25 is predominantly underexpressed in most tumors." (PMID 38570766, 2024). "The transmembrane coiled-coil domain containing protein 25 (CCDC25) was identified as a cancer cell surface receptor for extracellular DNA." (PMID 39704565, 2024). "NETs interact with coiled-coil domain-containing protein 25 (CCDC25) on tumor cells and enhance cancer cell motility by activating the integrin-linked kinase (ILK)-β-parvin pathway." (PMID 39795864, 2024). "CCDC25 is a transmembrane protein located on the cell membranes of cancer cells that can bind to NETs-DNA with high specificity and affinity, enabling cancer cells to sense NETs and thus promote distant metastasis." (PMID 38369519, 2024). "In the present study, CCDC25 was successfully downregulated at metastatic sites and significantly attenuated cancer metastasis." (PMID 38369519, 2024). "The interaction between NET formation DNA and CCDC25 promotes cancer cell migration and initiates metastasis by triggering intracellular signaling pathways." (PMID 38173719, 2023). "NETs-DNA activates the downstream ILK-β-parvin pathway by binding to CCDC25 transmembrane proteins on cancer cells, thereby enhancing cancer cell mobility." (PMID 37373412, 2023). "Study has shown that NET-DNA activates ILK-β-parvin pathway by binding to CCDC25, a transmembrane receptor on cancer cells, to enhance cell motility and thus promote cancer metastasis." (PMID 38012244, 2023). "NET-DNA scaffold recognition by Coiled-Coil Domain Containing 25 (CCDC25) in cancer cells can activate the ILK-β-parvin pathway to promote cancer cell proliferation and migration." (PMID 37143649, 2023).
cancer (continued). "NETs-DNA promotes cancer metastasis by interacting with the protein coiled-coil domain containing 25 (CCDC25)." (PMID 38022519, 2023). "Knockout or blockade of the CCDC25 protein can significantly inhibit NET-DNA-mediated metastasis of cancer cells, which confirms that CCDC25 is the receptor of NET-DNA." (PMID 37480055, 2023). "Previous study has identified the transmembrane protein CCDC25 on cancer cells as a specific sensor for NET-DNA25." (PMID 36253427, 2022). "In fact, citrullinated histones from NETs were found to promote cancer metastasis by binding to coiled-coil domain-containing protein 25 (CCDC25)." (PMID 35409152, 2022). "Another mechanism contributing to cancer metastasis is through the NET-DNA binding to CCDC25 on tumour cells, as reported in patients with breast cancer and patients with colon cancer." (PMID 35406451, 2022). "Based on their original studies, they explained how NETs interact with cancer cells and identified CCDC25 as a DNA sensor involved in the interaction between NETs and cancer cells." (PMID 36059520, 2022). "In neutrophils, NET formation depends on the generation of ROS by NADPH oxidase, which promotes cancer metastasis by trapping disseminating tumor cells and activating the CCDC25-ILK-β-parvin-RAC1-CDC42 cascade in cancer." (PMID 35739335, 2022). "Treatment of DNase I not only blocked NETs formation but also decreased CCDC25 expression in metastases, which indicates that inhibition of NETs formation disturbs the process by which cancer cells be attracted to the metastatic sites." (PMID 36253427, 2022). "CCDC25 was detected on cell membrane and in cytoplasmid, and was found high expressed [score value:12 (range, 2–12] in a primary cancer tissue from patient with ovary metastasis and in a liver metastatic tissue (case 1 and case 3)." (PMID 36253427, 2022). "Contrarily, overexpression of CCDC25 enhanced cancer cell adhesion and migration toward NET-DNA in vitro, and promoted the formation of lung and liver metastases in vivo." (PMID 35409152, 2022). "Other studies also suggested that neutrophil extracellular traps (NETs) promotes cancer metastasis via coiled-coil domain containing 25 (CCDC25)." (PMID 36171885, 2022). "Cholesterol biosynthesis greatly enhanced Coiled-coil domain containing protein 25 (CCDC25) expression on cancer cells as well as in lung metastases." (PMID 36253427, 2022). "The transmembrane protein CCDC25 was identified as the receptor on cancer cell surface to bind with surrounding NET-DNA promoting NETs formation." (PMID 36253427, 2022). "CCDC25 on cancer cell surface acts as a sensor and binding partner for NET-DNA; binding leads to activation of ILK–β-parvin–RAC1–CDC42 cascade, cytoskeleton remodeling and formation of distant metastases." (PMID 35574410, 2022). "Our data reveal that enhanced cholesterol biosynthesis promotes lipid raft-mediated CCDC25 expression on cancer cell membrane to benefit the formation of NETs." (PMID 36253427, 2022). "This was most likely connected to the NET-DNA receptor-transmembrane protein CCDC25 on the surface of cancer cells, which senses extracellular DNA and thus initiates the ILK-β-parvin pathway to enhance the motility of cancer cells." (PMID 35733158, 2022). "NET DNA binds to CCDC25 and induces an integrin linked kinase (ILK)-β-PARVIN-RAC1-CDC42 cascade, resulting in the metastasis of cancer cells." (PMID 34758877, 2021). "Other investigators were able to confirm significant correlation between NETs and liver metastases of patients with breast and colon cancers, thus confirming increased binding activity of transmembrane protein CCDC25 on primary cancer cells to NET DNA." (PMID 34503307, 2021). "CCDC25 is a membrane-bound protein and acted as a target molecule for the neutrophil extracellular traps (NETs)-mediated metastasis of cancer cells." (PMID 34067437, 2021).
cancer (continued). "NETs can also promote cancer metastasis to liver by binding to a transmembrane receptor, CCDC25, on cancer cells 12 to stimulate invasion." (PMID 34405029, 2021). "Importantly, we demonstrate that NET-DNA sensor CCDC25 is indispensable in NET-mediated treatment resistance by inducing cancer cell epithelial-mesenchymal transition via pyruvate kinase isoform M2–mediated STAT3 phosphorylation." (PMID 41480760, 2026). "Additionally, P. gingivalis influences the tumor immune microenvironment by inducing neutrophil extracellular traps (NETs), which stimulate cancer cell migration through NET-DNA-mediated chemotaxis of DNA sensors such as CCDC25." (PMID 40843171, 2025). "Another potential intervention strategy may be based on targeting the transmembrane NET-DNA receptor CCDC25, thus reducing cancer invasiveness." (PMID 38817858, 2024). "NET-DNA can bind to coiled-coil domain containing protein 25 (CCDC25) on cancer cells, activating the integrin-linked kinase (ILK)-β-parvin-ras-related C3 botulinum toxin substrate 1 (RAC1)-cell division control protein 42 (CDC42) cascade within cancer cells." (PMID 39143953, 2024). "Given that CCDC25 is reported to be a receptor for NET DNA, we tested whether CTSG enters cancer cells through CCDC25-mediated NET DNA-CTSG complex internalization." (PMID 38194275, 2024). "al found that, the transmembrane protein coiled-coil domain containing 25 (CCDC25) functions as a receptor for NETs-DNA on the surface of cancer cells, activating the ILK/β-parvin/RAC1 pathway and enhancing cancer cell motility by sensing extracellular NETs-DNA." (PMID 38664728, 2024). "Therefore, targeted inhibition of CCDC25 at tumor sites is expected to be a new and efficient cancer treatment strategy." (PMID 38369519, 2024). "NETs may directly support metastasis formation by trapping tumor cells at the distant site through the coiled-coil domain containing protein 25 (CCDC25), which can bind to NETs and is expressed on certain cancer cells (colorectal, breast, prostate, liver)." (PMID 36755071, 2023). "In addition, NETs can promote cancer metastasis by binding to CCDC25, a receptor on the surface of cancer cells." (PMID 37254661, 2023). "Additionally, tumor cells exhibited enhanced chemotaxis towards the DNA component of hepatic NETs through high-affinity binding with a transmembrane protein called CCDC25, which is expressed on carcinoma cells." (PMID 38173719, 2023). "Interestingly, CCDC25 was also significantly underexpressed in HCC in the HCCDB pan-cancer analysis." (PMID 36211267, 2022). "Additionally, they are also implicated in metastasis via coiled-coil domain containing protein 25 (CCDC25); proliferation, by transfer of neutrophil elastase (NE) to cancer cells and immunosuppression, by TGF-β and GCS-F signalling in neutrophils." (PMID 35406451, 2022). "Furthermore, the authors have identified the protein CCDC25 expressed at the surface of cancer cells as a specific sensor of NETs DNA, and responsible for malignant cells migration, adhesion and proliferation induced by NETs." (PMID 35309358, 2022). "Alongside this, it has been suggested that the NET’s DNA component (NET-DNA) could act as a chemotactic factor that attracts cancer cells via the transmembrane protein CCDC25 expressed on cancer cells, which recognizes extracellular DNA." (PMID 35159247, 2022). "However, the DNA component of NETs (NET-DNA) can promote cancer metastasis through coiled-coil domain containing protein 25 (CCDC25), a specific DNA sensor." (PMID 34804066, 2021). "NETs may stimulate cancer cell migration through the chemotactic effect of NET-DNA (a chemokine that attracts cancer cells) on DNA sensors, such as CCDC25 (a transmembrane protein), and the targeting of CCDC25 may be an attractive therapeutic strategy to prevent metastasis." (PMID 40843171, 2025).
cancer (continued). "Considering the interplay between NETs and HAoECs’ activation, as well as recent data suggesting that coiled-coil domain containing protein 25 (CCDC25) acts as NET-DNA sensor in cancer cells, we investigated whether CCDC25 expression is altered in HAoECs upon stimulation with EH-NETs." (PMID 34324440, 2021). "In addition, CCDC25 was recently observed to promote cancer metastasis." (PMID 34055889, 2021). "Our study reveals that NET-DNA promotes STAT3 phosphorylation via CCDC25, thereby facilitating cancer cell EMT and chemoresistance, consistent with the fact that cancer cell EMT reduces chemotherapeutic sensitivity." (PMID 41480760, 2026). "NET DNA binds to CCDC25 to activate the ILK-β-parvin pathway and enhance the aggressive behavior of cancer cells." (PMID 40568594, 2025). "Upon binding of NET DNA, CCDC25 activates the ILK–β-parvin pathway, enhancing cell motility and promoting cancer metastasis." (PMID 39704565, 2024). "Yang and colleagues discovered a transmembrane protein called Coiled-Coil Domain-Containing Protein 25 (CCDC25), which serves as a receptor for NET-DNA on cancer cells." (PMID 38817858, 2024). "As a result, ligand‐specific activation of the transmembrane protein CCDC25 triggers the ILK–β‐Parvin–RAC1–CDC42 cascade, which enhances tumor cell motility and eventually promotes cancer metastasis." (PMID 39015554, 2024). "In cancer cells, the NET-DNA receptor CCDC25 senses extracellular DNA and promotes cell mobility through the ILK–β-parvin pathway." (PMID 36059520, 2022). "These authors proved that CCDC25 senses extracellular DNA and, subsequently, activates the ILK-β-parvin pathway to attract cancer cells." (PMID 34503307, 2021). "Further studies on specific downstream pathways of this CCDC25-ILK-β-Parvin signalling would be needed for development of anti-metastatic drugs that target and block the NET-cancer interaction." (PMID 33596197, 2021). "In addition to functioning as a receptor for NET-DNA, CCDC25 also activates the ILK-β-PARVIN pathway, attracting cancer cells and enhancing their motility." (PMID 38817858, 2024). "Further study revealed that NET-DNA interact with coiled-coil domain-containing 25 (CCDC25) to activate the ILK-β-parvin-RAC1-CDC42 pathway, which may further facilitate the metastasis of cancer cells." (PMID 36993957, 2023). "Proteins extracted from the cytoplasmic membrane of cancer cells and then inoculated with NET DNA were examined, and the transmembrane protein coiled-coil domain containing protein 25 (CCDC25) was found to function as a potential receptor for NETs to promote tumor metastasis." (PMID 34758877, 2021). "If CCDC25 is involved in the citrate cycle, to which cancer cells are not prone, it may explain its downregulation in HCC." (PMID 36211267, 2022). "However, the knockout of CCDC25 did not impair the entrance of CTSG into cancer cells." (PMID 38194275, 2024).
tumor (40 papers, 2021 to 2026). "Promote tumor cell proliferation, migration, invasion, and angiogenesis; CCDC25 is associated with poor prognosis." (PMID 40564191, 2025). "The downregulation of CCDC25 is associated with advanced tumor stage and poor prognosis in ccRCC patients." (PMID 38570766, 2024). "Indeed, NETs can provide a physical shield that protects tumor cells from T and NK cell-mediated immune attack, or directly support tumor cell proliferation and invasiveness by activating the CCDC25-integrin linked kinase-β-parvin pathway or TGF-β signaling cascade." (PMID 35844591, 2022). "Here we identify the membrane NET-DNA sensor CCDC25 as a pro-tumor mediator and promising therapeutic target because of its increased accessibility and maximum maintenance of immune activation." (PMID 41480760, 2026). "Multivariate analysis revealed that high CCDC25 expression and tumor depth were independent predictors of both RFS and OS." (PMID 39953349, 2025). "Overall, VNP-shCCDC25 effectively knocked down CCDC25 and its downstream prometastatic signaling pathway after the successful invasion of tumor cells, which in turn reduced their invasiveness." (PMID 38369519, 2024). "CCDC25 expression levels in tumor vs. normal tissues were quantified using Western blot and immunofluorescence studies." (PMID 38570766, 2024). "Further paired analysis revealed that the expression of CCDC25 in tumor regions is significantly lower within the same patient than in normal tissues." (PMID 38570766, 2024). "Transwell assay results indicated that the migration ability of tumor cells markedly declined upon overexpression of CCDC25." (PMID 38570766, 2024). "We have provided evidence that CCDC25 acts as a tumor suppressor by inhibiting cell proliferation, migration, and promoting apoptosis." (PMID 38570766, 2024). "Using Western blot (WB) analysis, we measured the expression levels of CCDC25 and found that its expression was notably lower in tumor tissues compared to the adjacent normal tissues." (PMID 38570766, 2024). "CCDC25 acts as a potential tumor suppressor in ccRCC by inhibiting cell proliferation and migration, potentially through regulating the Hippo signaling pathway." (PMID 38570766, 2024). "EDU staining results revealed a notable decrease in EDU-positive cells following CCDC25 overexpression, further confirming that CCDC25 overexpression inhibits the proliferative capacity of tumor cells." (PMID 38570766, 2024). "Specifically, NETs-DNA first binds to CCDC25 on the surface of tumor cells, which in turn enhances the invasiveness of tumor cells by activating the prometastatic ILK-Parvb-RAC1-CDC42 signaling cascade." (PMID 38369519, 2024). "By liquid chromatography coupled with mass spectrometry assay, the coiled‐coil domain‐containing protein 25 (CCDC25) on the tumor surface was identified as a NET‐DNA receptor that recognizes the specific molecular structures of extracellular DNA." (PMID 39015554, 2024). "While cholesterol can still be taken in from the tumor microenvironment, tumor cell intrinsic cholesterol biosynthesis promotes metastasis and recurrence via CCDC25." (PMID 39062731, 2024). "Further immunofluorescence studies also demonstrated that the expression of CCDC25 within tumor tissues was significantly lower than that in the adjacent normal renal tissues." (PMID 38570766, 2024). "When categorizing patients based on tumor grade and staging, we found that as the tumor grade/stage increases, CCDC25 expression gradually diminishes." (PMID 38570766, 2024). "In this study, we aimed to deliver an encapsulated nucleic acid drug to the tumor site via delivery of VNP to ultimately achieve the goal of targeting the CCDC25 gene and thus inhibiting tumor metastasis." (PMID 38369519, 2024). "In multiple mouse models, NETs have been reported to recruit tumor cells to pre-metastatic niches via CCDC25." (PMID 36788538, 2023). "have reported that CCDC25 enhances metastasis via activation of the ILK‐β‐parvin pathway in tumour cells." (PMID 36254394, 2022).